ASPH (aspartate beta-hydroxylase)
Diseases named in the same sentence as ASPH in open-access papers (continued):
Sharing a sentence is not in itself a finding about the gene and the disease.
Traboulsi syndrome (7 papers, 2020 to 2025). "Overall, the combined results provide proof of concept that 2OG derivatives have the potential to alter catalysis of Traboulsi syndrome–associated AspH active site variants in a manner to, at least in parts, compensate for their reduced catalytic activity." (PMID 41354343, 2025). "The biochemical and biophysical results on the investigated Traboulsi syndrome–associated AspH variants expand knowledge on the active site requirements for productive catalysis of 2OG oxygenases." (PMID 41354343, 2025). "The combined results reveal the ability of cellular abundant 2-oxoacids other than 2OG, including amino acid transamination products, to, at least, partially rescue the activity of Traboulsi syndrome–associated AspH variants in vitro." (PMID 41354343, 2025). "SNPs affecting the ASPH gene, which encodes for the 2-oxoglutarate (2OG)-dependent oxygenase aspartate/asparagine-β-hydroxylase (AspH), are associated with Traboulsi syndrome." (PMID 41354343, 2025). "Screening of potential 2OG cosubstrate substitutes reveals that certain 2-oxoacids, including naturally present metabolites, manifest enhanced catalytic efficiency of Traboulsi syndrome–associated AspH variants compared with 2OG." (PMID 41354343, 2025). "The mechanism(s) by which reduced levels of AspH catalysis cause the phenotypes associated with Traboulsi syndrome are unclear, including because >100 human proteins contain EGFDs with the consensus sequence required for productive AspH catalysis." (PMID 41354343, 2025). "Three Traboulsi syndrome–associated SNPs affect ASPH codons encoding for AspH active site residues directly involved in 2OG binding, i.e., R688Q, R735Q, and R735W." (PMID 41354343, 2025). "We report studies on the clinically observed Traboulsi syndrome–associated R688Q, R735Q, and R735W AspH variants." (PMID 41354343, 2025). "Having shown that both the R688Q and R735Q AspH variants manifest reduced activity, we investigated the consequences of the Traboulsi syndrome–associated active site variations on the AspH fold and 2OG binding using crystallography." (PMID 41354343, 2025). "Genetic analysis identified a pathogenic ASPH variant (NM_004318.3:c.1892G>A, p.Trp631*) and a novel likely pathogenic variant (deletion of exons 20–21), confirming Traboulsi syndrome." (PMID 39336711, 2024). "This case report describes the clinical and genetic findings in a Mexican male with Traboulsi syndrome, highlighting the identification of a novel ASPH variant." (PMID 39336711, 2024). "The identification of pathogenic and novel ASPH gene variants expands our understanding of the genetic basis of Traboulsi syndrome and its variability." (PMID 39336711, 2024). "Individual analyses were performed and, unexpectedly, a homozygous variant in ASPH (NM_004318.3:c.1695C > A; p.(Tyr565*)) associated with AR Traboulsi syndrome was identified in the aunt." (PMID 35970915, 2022). "This is the first report of Traboulsi syndrome in a Chinese patient, and our study expands the spectrum of ASPH variants and provides information for clinical genetic counseling to this family." (PMID 33217155, 2021). "By using whole‐exome and Sanger sequencing, a novel mutation in ASPH associated with Traboulsi syndrome was identified." (PMID 33217155, 2021). "Mutations in the ASPH gene lead to Traboulsi Syndrome in humans, reported in four families in the literature." (PMID 35004304, 2021). "In 2014, Traboulsi syndrome was found to be linked to ASPH, an enzyme that hydroxylates asparagine‐ and aspartate‐residues on epidermal growth factor (EGF) domains of proteins." (PMID 33217155, 2021). "Kinetic studies with selected 2OG derivatives and hydrophobic 2-oxoacids bearing a single carboxylate group were performed using SPE–MS to quantify their efficiency in sustaining catalysis of the Traboulsi syndrome–associated AspH variants and to rank their therapeutic potential." (PMID 41354343, 2025).
Traboulsi syndrome (continued). "Although the R735Q AspH kcatapp/Kmapp value for 2OS was ∼250-fold lower than that of wt AspH for 2OG, the results clearly reveal the potential of (naturally occurring) 2OG derivatives for, at least, partially rescuing the activity of Traboulsi syndrome–associated AspH variants." (PMID 41354343, 2025). "The results thus raise the question as to whether the severity of Traboulsi syndrome–associated phenotypes varies among individuals bearing the R688Q or R735Q/W AspH variants." (PMID 41354343, 2025). "Interestingly, R735W AspH was inactive under all the tested conditions, supporting the proposal that developmental defects associated with Traboulsi syndrome are a direct consequence of impaired AspH catalysis." (PMID 41354343, 2025). "This analysis revealed a pathogenic variant in the ASPH gene, NM_004318.3:c.1892G>A (p.Trp631*), and a novel, likely pathogenic, variant characterized by the deletion of exons 20–21, confirming a compound heterozygous state consistent with Traboulsi Syndrome." (PMID 39336711, 2024). "This novel ASPH variant expands the known genetic heterogeneity of Traboulsi syndrome." (PMID 39336711, 2024). "The resultant loss of function could lead to the developmental anomalies associated with ASPH-related disorders, such as those observed in Traboulsi syndrome." (PMID 39336711, 2024). "Up to now, several ASPH variants have been reported to cause Traboulsi syndrome." (PMID 33217155, 2021). "Thus, it is, at least in principle, possible that the Traboulsi syndrome–associated variations in the AspH active site alter the consensus mechanism for 2OG oxygenases, i.e., they perturb the preferred ordered sequential binding of 2OG, then substrate, and then O2 to the active site." (PMID 41354343, 2025). "Thus, the substitution of the R735 guanidinium group has apparently a more pronounced effect on AspH catalysis than the R688Q substitution, potentially indicating why Traboulsi syndrome–associated SNPs in the ASPH codon for R735 are apparently more frequently detected than SNPs in other ASPH codons." (PMID 41354343, 2025). "Given that wt AspH acts on multiple EGFDs, the specific set of EGFDs involved in Traboulsi syndrome is hard to define, with competition between substrates, as proposed for FIH, being a possible factor." (PMID 41354343, 2025). "ASPH also encodes for multiple C-terminally truncated isoforms lacking the catalytic 2OG oxygenase domain, e.g., junctate, junctin, and humbug, that have roles inter alia in Ca(II) binding, dysregulated levels of which could potentially result in the phenotypes associated with Traboulsi syndrome." (PMID 41354343, 2025). "Traboulsi syndrome–linked nonsense terminations in ASPH resulting in C-terminally truncated AspH variants lacking the 2OG oxygenase domain imply that the associated phenotypes are a result of impaired AspH catalysis." (PMID 41354343, 2025). "The proposal that the developmental defects associated with Traboulsi syndrome are a result of impaired AspH catalysis has, however, not yet been validated at a biochemical level using purified AspH variants." (PMID 41354343, 2025). "Here, we present a male with Traboulsi syndrome with a milder ophthalmic phenotype and no spontaneous filtering blebs, and report the identification of one pathogenic and one novel ASPH variant." (PMID 39336711, 2024). "Although it is difficult to correlate the DURS1-associated phenotypes to a specific gene because of its genetic heterogeneity, the overlapping phenotypes of Traboulsi syndrome and DURS1 are striking and the role of ASPH in DURS1 should be investigated." (PMID 41354343, 2025). "Thus, given the common symptoms of Traboulsi syndrome, the available evidence suggests that the disease is a result of impaired catalysis/EGFD hydroxylation as catalyzed by AspH." (PMID 41354343, 2025).
colorectal cancer (5 papers, 2020 to 2025). A primary or metastatic malignant neoplasm that affects the colon or rectum. "This is consistent with the study showing greater efficacy of a second-generation ASPH inhibitor than a third-generation inhibitor in colorectal cancer." (PMID 38817852, 2024). "A unique study on human tissue microarrays immunohistochemically evaluated the expression of a truncated form of ASPH, Humbug, on a cohort of stage II colorectal carcinoma (CRC)." (PMID 32295249, 2020). "In colorectal cancer, ASPH gain or amplification was found in 56% of samples." (PMID 32811566, 2020).
pancreatic ductal adenocarcinoma (5 papers, 2015 to 2024). An infiltrating adenocarcinoma that arises from the epithelial cells of the pancreas. "Patient-derived xenograft (PDX) models of human pancreatic ductal adenocarcinoma (PDAC) were established to illustrate in vivo antitumor effects of the third-generation small molecule inhibitor specifically against ASPH’s β-hydroxylase activity." (PMID 31888763, 2019). "This study examines the expression of ASPH in human PC cell lines and pancreatic ductal adenocarcinoma (PDAC) tumor tissues, as well as determines how ASPH activates Notch signaling as a major contributor to generation of malignant phenotypes." (PMID 25483102, 2015). "A previous study in pancreatic ductal adenocarcinoma showed that ASPH could activate SRC signaling in cancer cells." (PMID 38817852, 2024). "Previous studies revealed that ASPH could promote the EMT process of cancer cells via SRC signaling activation in pancreatic ductal adenocarcinoma." (PMID 36982561, 2023).
lung adenocarcinoma (4 papers, 2020 to 2025). A carcinoma that arises from the lung and is characterized by the presence of malignant glandular epithelial cells. "In this study, we identified a circular form of ASPH RNA (circASPH), expression of which was upregulated in lung adenocarcinoma and the human lung adenocarcinoma cell lines." (PMID 32719345, 2020). "In this study, we identified a circular form of aspartate beta-hydroxylase (ASPH) RNA (circASPH), which was upregulated in lung adenocarcinoma." (PMID 32719345, 2020). "CircASPH (Aspartate Beta-Hydroxylase) expression is upregulated in lung adenocarcinoma and, finally, circFUT8 (Fucosyltransferase 8) functions as a tumor suppressor in bladder cancer cells where low circFUT8 was associated with poor prognosis, high histological grade, and lymph node metastasis." (PMID 33920880, 2021).
lymph node metastasis (4 papers, 2021 to 2025). "Findings from 275 gallbladder cancer patients in this study demonstrated that ASPH-positive individuals had a higher incidence of lymph node metastasis and locoregional invasion when compared to ASPH-negative individuals." (PMID 40110547, 2025). "ASPH staining of 142 patients with primary HNSCC tumors, 10 patients with lymph node metastasis, and 3 patients with CIS were evaluated on our TMA." (PMID 38732216, 2024).
neuroblastoma (4 papers, 2006 to 2025). Neuroblastoma (NB) is the most common solid, extracranial childhood tumor. "Western blot analysis detected ASPH immunoreactivity in CS1 (Grade 3 conventional chondrosarcoma), CDS11 (Grade 2 conventional chondrosarcoma), CDS17 (de-differentiated chondrosarcoma), and CYZ/PNET2 neuroblastoma cells (positive control)." (PMID 40427168, 2025).
prostate carcinoma (4 papers, 2020 to 2023). A carcinoma that arises from epithelial cells of the prostate gland. "The PAN-301-1 vaccine against ASPH has already been tested in a phase 1 clinical trial in patients with prostate cancer." (PMID 32811566, 2020). "Moreover, a recent study reported an oxidative stress state of the castration-resistant prostate cancer cells upon ASPH overexpression which was reversed by silencing ASPH expression or generating hypoxic conditions resulting in impaired cell proliferation and invasion." (PMID 32811566, 2020). "ASPH is currently being targeted with an anti-ASPH nanoparticle vaccine, SNS-301, in a clinical trial in prostate cancer." (PMID 35004304, 2021).
ectopia lentis (3 papers, 2021 to 2025). "A previous study showed ASPH‐mediated hydroxylation of FBN1/LTBP2 may be associated with ectopia lentis." (PMID 33217155, 2021). "Genetic variants were identified in four genes: FBN1 (associated with Marfan syndrome and cardiovascular complications; n = 6), ADAMTSL4 (associated with non-syndromic ectopia lentis; n = 2), LTBP2 (n = 1) and ASPH (n = 1)." (PMID 37107549, 2023). "Note, however, that alterations in genes encoding for proteins that are not substrates of AspH also cause ectopia lentis." (PMID 41354343, 2025). "Interestingly, FBN1 SNPs that affect EGFD residues other than cysteines that are essential for AspH catalysis have also been reported to result in ectopia lentis." (PMID 41354343, 2025).
glioblastoma (3 papers, 2020 to 2025). The most malignant astrocytic tumor (WHO grade IV). "In glioblastoma, the prognostic significance of ASPH was suggested by profiling of alternative mRNA splicing." (PMID 32811566, 2020). "In hypoxic regions of glioblastoma, both HIF-1α and ASPH were highly expressed, particularly in more aggressive mesenchymal subtype of glioblastoma, suggesting a possible involvement of ASPH in mesenchymal transition." (PMID 32811566, 2020).
atherosclerosis (2 papers, 2020 to 2021). A disease characterized by the build-up of fatty material and calcium deposition in the arterial wall resulting in partial or complete occlusion of the arterial lumen. "A loop of has-circ-0028198/has-circ-0092317/XIST/miR-543/aspartate beta-hydroxylase or has-circ-0028198/has-circ-0092317/XIST/miR-543/phosphodiesterase 3B has been implicated in oxidized, low-density, lipoprotein-stimulated foam cells in atherosclerosis." (PMID 32293498, 2020).
bladder cancer (2 papers, 2019 to 2021). "ASPH has been reported as a potential therapeutic target for malignant glioma (PMID: 27981247), and LY6K is a novel bladder cancer molecular target that integrated genome-wide analysis (PMID: 21063397)." (PMID 31608231, 2019).
breast neoplasm (2 papers, 2019 to 2024). A benign or malignant neoplasm of the breast parenchyma. "ASPH was detectable at early stage breast neoplasm, i.e., preinvasive DISC (ductal carcinoma in situ), substantially enhanced from IDC (invasive ductal carcinoma) to advanced/spontaneously metastatic breast cancer." (PMID 31694640, 2019).
chondrosarcoma (2 papers, 2025). A malignant cartilaginous matrix-producing mesenchymal neoplasm arising from the bone and soft tissue. "We show that ASPH blockade with MO-I-1182 inhibits chondrosarcoma cell growth both in vitro and in vivo." (PMID 40149287, 2025). "Our findings identified aspartate β-hydroxylase (ASPH) as a biomarker in CS, as a factor in the metastatic phenotype, and as a potential treatment target for chondrosarcoma." (PMID 40149287, 2025). "Our results show that ASPH, an oncofetal protein, is expressed in chondrosarcoma and is a predictor of the development of metastasis and death." (PMID 40149287, 2025). "Our goal is to analyze the expression of ASPH in conventional chondrosarcoma, evaluate its utility as a biomarker, and determine if ASPH inhibition diminishes tumor progression in a preclinical model." (PMID 40149287, 2025). "We have identified the cell surface protein aspartate β-hydroxylase (ASPH) as another molecular target for chondrosarcoma." (PMID 40149287, 2025). "ASPH expression was also analyzed in normal primary chondrocytes, chondrosarcoma cells and cell lines, and PDX with Western blot." (PMID 40149287, 2025). "Our goals were to analyze the expression of ASPH in conventional chondrosarcoma, evaluate its utility as a biomarker, and determine if ASPH inhibition diminishes tumor progression in a preclinical model." (PMID 40149287, 2025). "Our results show that ASPH is expressed in human chondrosarcoma cell lines, primary tumors, PDX, and metastases." (PMID 40149287, 2025). "Because the cancer biology underlying carcinoma and sarcoma, the latter being derived from mesoderm, is different, we are surprised to find high expression of ASPH in chondrosarcoma." (PMID 40149287, 2025). "Similarly, preliminary studies also suggest that high-grade conventional chondrosarcomas express higher levels of ASPH than low-grade chondrosarcomas." (PMID 40427168, 2025). "Systemic treatment with an SMI directed against ASPH inhibits tumor progression in a preclinical model, suggesting that ASPH-targeted therapy may be a new treatment strategy for chondrosarcoma expressing ASPH." (PMID 40149287, 2025). "In light of the well-documented roles of Notch in many malignancies, including chondrosarcoma, ASPH could potentially serve as an excellent target for chondrosarcoma diagnostics and therapeutics." (PMID 40427168, 2025). "Our results suggest that ASPH-targeted therapy may be a new treatment strategy for chondrosarcoma." (PMID 40149287, 2025). "Inhibition of ASPH with an SMI decreased tumor progression in a preclinical model, suggesting that ASPH-targeted therapy may have potential for chondrosarcoma treatment in ASPH-expressing tumors." (PMID 40149287, 2025). "ASPH is a transforming cell surface receptor, but its role in chondrosarcoma has not been evaluated." (PMID 40149287, 2025). "Only the chondrosarcoma cells, cell lines, and PDX express ASPH at a high level." (PMID 40149287, 2025).
chronic pancreatitis (2 papers, 2015 to 2019). A chronic inflammatory process causing damage and fibrosis of the pancreatic parenchyma. "ASPH was undetectable in adult normal pancreas, inflammatory diseases (acute/chronic pancreatitis), or pancreatic neuroendocrine tumor." (PMID 31888763, 2019).
liver cancer (2 papers, 2022 to 2025). An epithelial or non-epithelial malignant neoplasm that arises from the liver. "Previous studies have indicated a significant association between ASPH and the recurrence of liver cancer, as it facilitates the migration and invasion of liver cancer cells." (PMID 40110547, 2025).
Malignant hyperthermia (2 papers, 2022 to 2025). Malignant hyperthermia is characterized by a rapid increase in temperature to 39-42 degrees C. Malignant hyperthermia may occur in response to either inhalational anesthetics such as halothane, to muscle relaxants such as succinylcholine, or to exercise. "Variants in specific genes, such as ASPH, which encodes junctin (a regulator of excitation–contraction coupling), have been linked to exertional heat illness and malignant hyperthermia susceptibility." (PMID 39806520, 2025). "In this study, we identified rare, pathogenic variants in junction (ASPH) as a novel genetic cause of exertional heat illness and malignant hyperthermia susceptibility." (PMID 35697689, 2022).
mastitis (2 papers, 2019 to 2021). Inflammation of breast tissue during lactation or postpartum due to an obstructed duct or infection. "ASPH was undetectable in normal breast, mastitis or benign breast tumor (intraductal papilloma or fibroadenoma)." (PMID 31694640, 2019). "A significantly associated SNP at BTA 14:27024015 lay within an intron of Aspartate Beta-Hydroxylase (ASPH), known for hydroxylating epidermal growth factors and contributing to dysmorphic features; this region has not been associated with mastitis or type traits previously." (PMID 33920522, 2021).